RN7SL57P (RNA, 7SL, cytoplasmic 57, pseudogene)
Gene: Miscellaneous RNA gene on chromosome 9 (112,242,550 to 112,242,839, reverse strand). Ensembl gene ENSG00000242256.
Homologues: Orthologues: chimpanzee Metazoa_SRP (99% identical), macaque Metazoa_SRP (88% identical), dog Metazoa_SRP (62% identical). Paralogues in human: RN7SL1 (84% identical), RN7SL2 (84% identical), RN7SL3 (84% identical), RN7SL45P (82% identical), RN7SL650P (80% identical), RN7SL712P (80% identical), RN7SL748P (80% identical), RN7SL769P (80% identical), RN7SL145P (80% identical), RN7SL326P (80% identical), RN7SL444P (80% identical), RN7SL479P (80% identical), and 707 more.